KRAS (KRas proto-oncogene, GTPase)
Diseases named in the same sentence as KRAS in open-access papers (continued):
Sharing a sentence is not in itself a finding about the gene and the disease.
cancer (continued). "In addition to point mutation KRAS, allelic imbalances are also frequent in human cancers leading to the predominance of a mutant allele." (PMID 32725342, 2020). "Numerous studies have shown that mutations in the KRAS oncogene may play a key role in the development of different cancers." (PMID 32059456, 2020). "Together, our data support that cycles of FMD plus pharmacological doses of vitamin C could represent a promising therapeutic opportunity to be tested in the clinic for the treatment of KRAS mutated cancers." (PMID 32393788, 2020). "These include cancers of the lung or colon which frequently display KRAS mutation." (PMID 32825312, 2020). "These epigenetically altered genes associated with KRAS expression could represent potential therapeutic targets in KRAS-driven cancer." (PMID 32576853, 2020). "Interestingly, this patient presenting amplification of the ASH2L gene (patient ID: TCGA-2G-AAF6), also presented a KRAS G12V mutation, a mutation that is well-known to negatively impact overall cancer survival and relapse." (PMID 33257682, 2020). "The challenge, however, is that the level of DNA associated with a mutant form of KRAS may be very low relative to the amount of wild-type KRAS DNA, even in a cancer patient." (PMID 32059456, 2020). "Furthermore, high expression levels of MMP25 were associated with many pathways in cancer, for instance, KRAS signaling pathway, apoptosis, PI3K/AKT/mTOR signaling pathway, and JAK/STAT signaling pathway." (PMID 32850314, 2020). "Somatic KRAS mutations that introduce amino acid substitutions at codons 12, 13, and 61 are highly prevalent in cancer and encode oncoproteins that accumulate in the active, GTP-bound conformation due to reduced rates of intrinsic GTP hydrolysis and resistance to GTPase-activating proteins (GAPs)." (PMID 32990679, 2020). "AZD4785 is a cET-ASO targeting KRAS, an oncogene that is often mutated in association with cancer." (PMID 32373584, 2020). "A total of 103 KRAS mutations have been found in 263 cancer patients." (PMID 32207862, 2020). "In this study, we developed a novel monoclonal antibody (mAb) recognizing the extracellular domain of human ASCT2, and investigated whether ASCT2 can be a therapeutic target for KRAS‐mutated cancers." (PMID 31709772, 2020). "Somatic KRAS mutations are highly prevalent in many cancers." (PMID 32990679, 2020). "Among the list of oncogenes, KRAS, which encodes a small GTPase called Kras 1, might be the most prevalent oncogene in human cancers." (PMID 33052229, 2020). "In addition, several studies reported for different cancer entities that KRAS amplified tumors are associated with poor prognosis." (PMID 32571252, 2020). "RAS mutations in all cancer types occur mostly in KRAS (85%), followed by NRAS (12%) and HRAS (3%)." (PMID 31941155, 2020). "In non recto-sigmoid cancers, high cholesterol was significantly associated with KRAS WT (OR 0.39, CI 0.15–0.97, p = 0.04), whilst there was a borderline association between MetS and KRAS mutation (OR 2.78, 95% CI 0.99–7.82, p = 0.05)." (PMID 32594310, 2020). "In addition, the CIF plots showed that KRAS mutation was a hazard factor for the CSS of patients with cancers in the location of left colon, right colon and rectum (p < 0.001)." (PMID 32547859, 2020). "Precise estimates were not feasible, such as high odds ratio and wide confidence intervals that include the one (the null hypothesis value) observed when evaluating associations between MetS and KRAS status in non recto-sigmoid cancers." (PMID 32594310, 2020). "The heterogeneity of KRAS mutant primary cancers is significant, affecting the variant allele frequency, which could lead to unpredictable branching development in metastases." (PMID 32725342, 2020).
cancer (continued). "Therefore, strategies to enhance and expand vitamin C activity in the treatment of KRAS mutated cancers are necessary." (PMID 32393788, 2020). "Mutations in KRAS are detected in approximately 30% of all human cancers." (PMID 32207862, 2020). "Rationale: KRAS is one of the most frequently mutated oncogenes in cancers." (PMID 32308773, 2020). "In pancreatic KRAS-mutated cancer cells, which can proliferate using albumin as the extracellular source of leucine, loss of SLC38A9 or its transport function strongly inhibited mTORC1 activation by macropinocytosed albumin as evidenced by cell proliferation and tumor formation." (PMID 33511116, 2020). "It further emphasizes that apparently unaffected colon mucosa may harbor cancer gene mutations and indeed KRAS mutations have been found in colonic effluent samples of patients at increased risk of CRC, however with normal finding on colonoscopy." (PMID 32380676, 2020). "Comparison of TKI sensitivity among these cell lines showed that EGFR/KRAS co-mutated cells were more sensitive than parent cells, indicating that EGFR-TKIs may represent a treatment option for cancers harboring EGFR/KRAS co-mutation." (PMID 32130260, 2020). "This indicates that signaling pathways downstream of constitutively active KRAS are necessary for the effects we observe after knockdown of Rab13 that could be similar in other cancer cells with KRAS mutations." (PMID 32978434, 2020). "This information may be important in the future when we are considering the prognostic or predictive power of these various KRAS mutations in various cancer types." (PMID 32725342, 2020). "Moreover, an association between TERT expression and KRAS mutation was shown in TAs, suggesting the development of drugs targeting this pathway for cancer prevention." (PMID 32932803, 2020). "Secondary events are required for potent ADM induction and progression to carcinoma, which include additional genetic alterations or enhancement of the activities of wild-type and mutant KRas alleles through chronic inflammation or upregulation of growth factor signalling." (PMID 32641778, 2020). "Compared to conventional carcinomas, SACs are characterized by a worse prognosis, weak development of the immune response, an active invasive front and a frequent resistance to targeted therapy due to a high occurrence of KRAS or BRAF mutation." (PMID 32183342, 2020). "Cancers may acquire activating mutations in exon 2 of KRAS, thus isolating the signaling pathway from the effect of upstream EGFR2, rendering the EGFR inhibitors ineffective." (PMID 30975211, 2019). "Thus, the precise identification of mutations in the KRAS gene and the encoded protein is extremely important for a clearer understanding of their effects on cancer cell proliferation and survival." (PMID 31117243, 2019). "Of three RAS isoforms, KRAS is the most frequently mutated in human cancers, and KRAS activation has been proved as an early oncogenic event in endometrial carcinogenesis, which correlates with mucinous differentiation in cancers." (PMID 30886832, 2019). "Thus, constructing a model that carries both APC and KRAS mutations is also important for thorough molecular evaluation of the cancer." (PMID 31766149, 2019). "However, given that KRAS is the most frequently mutated oncogene in a wide variety of cancers, the present work is likely to have a much wider impact." (PMID 31635338, 2019). "Interestingly, KRAS-mutant cancer cells dependent on or addicted to KRAS oncogene are more associated with an epithelial phenotype, whereas those independent of KRAS adopt a mesenchymal phenotype." (PMID 31612108, 2019). "Recently, the KRAS mutation has been reported in several human cancers." (PMID 31330954, 2019).
cancer (continued). "Notably, in human cancer, mutation of KRAS-G12D has been shown to generate a neoantigen that elicits CD8+ cytotoxic T cell responses." (PMID 30832732, 2019). "Here, cfDNA analysis revealed the KRAS mutation of the synchronous stage IV cancer of the pancreas." (PMID 31134762, 2019). "In this external validation study of previously proposed molecular subtype classifications for the prediction of survival among CRC patients, we found that MSS cancers with BRAF or KRAS mutations generally conferred a worse prognosis compared to tumors with no such mutations." (PMID 31296182, 2019). "However, though KRAS mutations are found in a wide range of cancers across nearly all lineages, selective KRAS inhibitors are not yet clinically available." (PMID 30691487, 2019). "KRAS mutations can promote all the key aspects of cancer cell metabolism." (PMID 31544066, 2019). "KRAS is one of the most frequently mutated genes in human cancers." (PMID 31009485, 2019). "This readaptation requires higher concentration of MEK inhibitors to achieve therapeutic response, with great limitation to their clinical use due to poor tolerability, and explains the disappointing results in early clinical studies exploring MEK inhibitors in KRAS-mutated cancers." (PMID 30691487, 2019). "Importantly, the two KRAS variants, KRAS4A and KRAS4B, have been described to both be expressed to varying degrees in human cancer tissue, and differ in their interaction with the PDEδ solubilization factor." (PMID 31712554, 2019). "Moreover, macropinocytosis is upregulated in KRas mutated cancer cells such as A549 cells, and therefore cancer cells with KRas mutations should be more sensitive to eATP’s induced EMT and cell movement." (PMID 31582910, 2019). "The mutation in the KRAS gene was found to be correlated with colorectal, pancreatic and lung cancer, and so identifying it could be used to differentiate cancer cells from healthy cells." (PMID 31817059, 2019). "KRAS is the most frequently mutated isoform accounting for about 20% of all human cancers." (PMID 31803624, 2019). "The hypothesis of ADCC as additional or alternative anti-cancer mechanism is supported by two mirror observations: i) a small percent of KRAS mutated mCRC patients respond to cetuximab and, ii) not all “all RAS” wt mCRC patients respond to anti-EGFR therapy." (PMID 31500586, 2019). "Fourteen of 31 tumors harboring KRAS mutation at codon 12 in at least 2 out of 5 analyzed samples revealed intratumor heterogeneity of this mutation defined as the coexistence of two different mutated sequences in cancer tissue." (PMID 30368666, 2019). "In addition, KRAS Gly12 (including G12V, G12C, and G12D) is also a classic cancer mutation, and the mutation frequency of this site in metastatic pancreatic and appendiceal cancers is more than 20%." (PMID 31781598, 2019). "Similarly, KRAS is often mutated in human cancers, and it drives similar growth and proliferation phenotypes." (PMID 31652979, 2019). "Moreover, it is desirable to identify the somatic mutations in the KRAS gene that can result in the development of cancer." (PMID 31117243, 2019). "Therefore, our results suggest that ARID1A is required for maintaining the expression of cancer-relevant downstream targets of the MEK/ERK pathway in KRAS-mutated CRC cells." (PMID 31217031, 2019).
cancer (continued). "In addition, crosstalk with other cancer-related signaling pathways, such as KRAS, APC, and LKB1 mutations, have all been reported to contribute to upregulate the YAP/TAZ activity in cancers." (PMID 30805310, 2019). "Interestingly, it has been shown that oncogenic KRAS signaling promotes a pro-tumorigenic microenvironment, and the associated crosstalk alters the expression profile of cancer cells." (PMID 31847096, 2019). "RAS allelic imbalance and loss of wild-type KRAS alleles can further extend the oncogenic properties of cancer cells and mark the most aggressive undifferentiated cells, but also create a dependency on the MAPK signaling pathway with unique sensitivities to pharmacologic MEK inhibition." (PMID 31681559, 2019). "He then was continued on maintenance 5-fluorouracil plus capecitabine-based chemotherapy for 5 months after which time his cancer progressed and a liquid biopsy at that time revealed a KRAS Q61H mutation which was felt to be acquired from prior therapy with cetuximab." (PMID 30923702, 2019). "However, they observed that combination of CDKN2A methylation and KRAS mutations independently predicted the risk of recurrence, thereby reducing overall and cancer-specific survival." (PMID 31390840, 2019). "KRAS is one of the three RAS isoforms that is most frequently mutated in human cancers." (PMID 31208154, 2019). "While there are three human RAS genes (HRAS, NRAS, and KRAS) that encode highly related 188–189 amino acid proteins, KRAS is the most frequently mutated oncogene in human cancers, accounting for up to 25% of lung, 40% of colorectal, and 95% of pancreatic cancers." (PMID 30644389, 2019). "Therefore, alternative strategies are needed to inhibit the most frequent mutations of KRAS accounting for 88% of KRAS mutant cancers." (PMID 31197133, 2019). "SNPs may also affect cancer susceptibility: an SNP on the 3′UTR of the critical proto-oncogene KRAS leads to the loss of let-7-mediated repression and subsequent upregulation of KRAS in non-small cell lung cancer (NSCLC) patients." (PMID 31847302, 2019). "KRAS mutated tumors have been mainly explored in metastatic CRCs and associated with a poor outcome, notably a low 5-year disease-free survival, but are also associated with a short cancer-specific survival in stage I CRCs." (PMID 31330830, 2019). "KRAS mutation is one of the most common mutations found in many types of cancers." (PMID 30679620, 2019). "In support of these findings, a preliminary improved anti-cancer response was observed in a CRC PDX harboring mutated KRAS with intrinsically high AKT activity using GC1118 combined with the dual PI3K/mammalian target of rapamycin (mTOR)/AKT inhibitor BEZ-235, without observed toxicity." (PMID 31771279, 2019). "However, more discrepancies (n = 7) were observed between blood and positive cancer tissue for mutated KRAS sequences." (PMID 30368666, 2019). "In normal cells, KRAS-activity is tightly controlled, but with specific mutations, the KRAS protein is persistently activated, giving cells a growth advantage resulting in cancer." (PMID 31399087, 2019). "In this case, PD-L1 increased expression was associated with immune evasion, indicating that KRAS mutant cancers could indeed benefit from treatment with anti-PD-L1 or anti-PD-1 immune checkpoint inhibitors." (PMID 31847096, 2019). "We also considered other common mutations in cancer namely KRAS, PTEN and PI3K." (PMID 30728400, 2019). "Notably, pancreatic (95%), colorectal (45%), and lung (35%) cancers harbor KRAS mutations at remarkably high frequencies." (PMID 31878223, 2019). "Furthermore, KRAS mutations were identified in a small number of samples from the histologically normal colonic mucosa adjacent to carcinomas." (PMID 31781186, 2019). "Finally, KRAS G12V mutations were the second most common KRAS mutation type in serrated colorectal carcinoma, a carcinoma type characterized by MIPs." (PMID 31545494, 2019).
cancer (continued). "In addition to RAS, activating mutations in the BRAF gene have been found in 8–10% of CRC cancers, and they are almost always mutually exclusive with KRAS mutations." (PMID 29881714, 2018). "Based on the results, we hypothesized that if indels and frameshifts of KRAS occur due to the specific sgRNAs, this would affect cell viability of cancer cells with KRAS mutations." (PMID 30089886, 2018). "Even if further studies are needed, we propose that NP tethering could expand application of the anti-EGFR antibody to a wider number of cancer patients including the KRAS-mutated ones, currently suffering from poor prognosis." (PMID 30287819, 2018). "It has been reported that 18F-FDG accumulation reflects the KRAS mutational status of cancers." (PMID 29642912, 2018). "Given the comprehensive genetic background of KRAS alteration across different cancer types, we further tested whether KRAS gene mutation will influence the prognosis of the disease." (PMID 30406144, 2018). "The gene KRAS is frequently mutated in various human cancers." (PMID 30199525, 2018). "In addition, we found that TGF-β–Smad pathway engages in crosstalk with the STAT3 pathway in cancer cells harboring a KRAS mutation." (PMID 29969465, 2018). "Mutations within the KRAS oncogene are associated with the proliferation of various cancers." (PMID 30089886, 2018). "Therefore, our study suggests that the MYC-mediated sensitivity of KRAS-mutated cancer cells to BET inhibition is highly context dependent and that such effectivity relies on more than one molecular mechanism." (PMID 29721157, 2018). "In addition, multiple KRAS mutations were detected in the same cancer cells, possibly implying that a second KRAS mutation occurred due to selective advantage and leading to stronger KRAS signaling." (PMID 29386069, 2018). "A common cancer-associated mutation occurs in KRAS at the glycine-encoding codon-12." (PMID 30089886, 2018). "Mutation-driven activation of KRAS is crucial to cancer development." (PMID 29755673, 2018). "Whether the recognition of non-endogenous (except in 1/8 specimen) KRAS mutations represents an ongoing or a past evolution of cancer cells with mutant KRAS has to be evaluated." (PMID 30283732, 2018). "The class 1 BRAF V600E mutation and also class 2 mutations allow for constitutive activation of the pathway; therefore, a concurrent KRAS mutation is redundant which is indicated by the mutual exclusivity of these two mutation types occurring in a single cancer." (PMID 30598662, 2018). "However, the mutational status of the KRAS gene across different cancer types still remains largely veiled." (PMID 30406144, 2018). "However, the complexity of KRAS mutation landscape across different cancer types and the mosaic effect caused by cancer cellularity and heterogeneity make the choice of KRAS genotyping method a challenging topic in the clinical practice." (PMID 30406144, 2018). "Moreover, recent studies revealed interaction of APC and KRAS mutations in the various stages of colorectal tumorigenesis and even in metastasis accompanying activation of the cancer stem cells (CSCs)." (PMID 29872723, 2018). "KRAS testing was closely associated with proximity to NCI cancer centers." (PMID 29554880, 2018). "We report here that DMF is preferentially cytotoxic against KRAS mutated cancer cells." (PMID 29507676, 2018). "The snapback primer assay is a reliable, sensitive method to detect the major mutant KRAS alleles, which might facilitate the effective cancer treatment decisions." (PMID 30406144, 2018). "Indeed, a recent study revealed that KRAS showed imbalanced allelic expression in TCGA LUAD cancer type by comparing variant allele frequencies between DNA and RNA." (PMID 29504894, 2018). "However, a recent study that stratified a large cohort of stage III cancers for MMR status and BRAF and KRAS mutations found that MSS cancers with a BRAF mutation had a similarly poor 5-year survival rate as MSS cancers with a KRAS mutation." (PMID 30598662, 2018).